PLK1 (polo like kinase 1)
Diseases named in the same sentence as PLK1 in open-access papers (continued):
Sharing a sentence is not in itself a finding about the gene and the disease.
bladder cancer (continued). "PLK1 siRNA hindered the proliferation, invasion and migration of bladder cancer cells, as determined by the MTT, BrdU and transwell assays." (PMID 29246203, 2017). "The downstream genes and pathways of PLK1 in bladder cancer cells were identified by GO and KEGG enrichment analysis and a protein-protein interaction network." (PMID 29246203, 2017). "To determine the key genes regulated by PLK1 in bladder cancer cells, we further analyzed the significantly altered genes related to cell proliferation, invasion and migration." (PMID 29246203, 2017). "We previously determined that PLK1 plays an important role in the carcinogenesis and development of bladder cancer." (PMID 29246203, 2017). "In this study, we found that the proliferation, invasion and migration of bladder cancer cells decreased upon PLK1 knockdown." (PMID 29246203, 2017). "RO3280 suppressed bladder carcinoma growth by inducing G2/M arrest and mitotic arrest and ultimately induced apoptosis and mitotic catastrophe through inhibiting PLK1 activity, which activates the signalling molecules that are negatively regulated by PLK1." (PMID 27878946, 2017). "We performed protein-protein interaction analysis to select five important candidate genes (BUB1B, CCNB1, CDC25A, FBXO5, KIF20A, NDC80) regulated by PLK1 in bladder cancer cells using STRING software." (PMID 29246203, 2017). "Our findings provide a rationale for evaluating the function of this novel PLK1 inhibitor in bladder carcinoma." (PMID 27878946, 2017). "KEGG and GO analysis then suggested that PLK1 mainly modulates genes related to the cell cycle and cell migration and invasion in bladder cancer." (PMID 29246203, 2017). "Exosomes can also deliver PLK-1 siRNA into bladder cancer cells to silence PLK-1, reducing their proliferation." (PMID 28127287, 2016). "Patients with urinary bladder cancers expressing high levels of PLK-1 have a poor prognosis compared with patients with its low expression." (PMID 21884621, 2011). "TCGA data indicated that the patients with high PLK1 expression in lung adenocarcinoma, renal clear cell carcinoma, and bladder cancer exhibit shorter overall survival, whereas the patients with high PLK1 expression in squamous cell carcinoma, rectal cancer, and thymoma exhibit a better prognosis." (PMID 36267311, 2022). "Above all, our results showed that efficient siRNA-mediated PLK1 knockdown might inhibit the proliferation, invasion and migration of bladder cancer cells." (PMID 29246203, 2017). "Therefore, the objective of this study was to determine the pre‐clinical effects of targeting PLK1 in bladder cancer in vitro and in vivo." (PMID 27878946, 2017). "However, FBXO5 was negatively regulated by PLK1, which was associated with important clinicopathological characteristics, and FBXO5 siRNA promoted bladder cancer cell proliferation, invasion and migration." (PMID 29246203, 2017). "Together, these results reveal that reduced PLK1 expression may attenuate the proliferation ability of bladder cancer cells." (PMID 29246203, 2017). "Although further laboratory and pre‐clinical investigations are needed to corroborate these data, our demonstration of bladder cancer growth inhibition and dissemination using a pharmacological inhibitor of PLK1 provides new opportunities for future therapeutic intervention." (PMID 27878946, 2017). "Moreover, the histologically high-grade, deeply invasive, lymphatic-invasive, and venous-invasive bladder cancers demonstrated significantly higher PLK-1 expression." (PMID 21884621, 2011). "Similarly, Intravesical administration of Plk1 siRNA suppressed bladder cancer growth in an orthotopic bladder cancer mouse model." (PMID 19161615, 2009). "Also Plk1 has been reported to be regulated by E2F3 in bladder cancer cells in addition to known E2F3 targets such as Cyclin A and novel targets including pituitary tumor transforming gene 1 (PTTG1), and Caveolin-2." (PMID 19883508, 2009).
bladder cancer (continued). "Specifically, CDK1, with an AUC value of 0.93, followed by PLK1 at 0.91 and AURKB at 0.90, showed the largest areas under the ROC curve, indicating their strong potential for distinguishing between bladder cancer and normal samples." (PMID 39456780, 2024). "In an in vitro study, it was noted that the bladder cancer cells internalized the HEK293 exosomes more than normal bladder cells, which led to a successful knockdown of PLK-1 mRNA and protein." (PMID 34067896, 2021). "The exosomes were loaded with polo-like kinase 1 (PLK1) siRNA via electroporation and then co-cultured with UMUC3 metastatic bladder cancer cells." (PMID 34067896, 2021). "In this study, the anti‐tumour activities of a novel Polo‐like kinase 1 (PLK1) inhibitor (RO3280) was evaluated in vitro and in vivo in the bladder carcinoma cell lines 5637 and T24." (PMID 27878946, 2017). "The two bladder carcinoma cell lines displayed low EC50 values and expressed high levels of PLK1, the molecular target for RO3280." (PMID 27878946, 2017). "Recently, Plk1 has been reported to be regulated by E2F3 transcription factor, a partner of pRb in the regulation of cell cycle transitions, in bladder cancer cells in addition to known E2F3 targets such as Cyclin A." (PMID 20003272, 2009). "The expression of PLK1, GATA3, and CD40 were even related to the prognosis of bladder cancer." (PMID 36425941, 2022).
colon carcinoma (41 papers, 2004 to 2025). "To test this possibility, we utilized The Cancer Genome Atlas (TCGA) to identify 104 colon cancer patient samples harboring APC non-sense mutations for which PLK1 expression and clinical meta-data was also available." (PMID 29549256, 2018). "The combination of CPT11 with PLK1 targeting agents was previously assessed in neuroblastoma and colon carcinoma xenografts, although the molecular mechanisms underlying the antitumor efficacy were not elucidated." (PMID 25826089, 2015). "It was recently reported that mutations in the PLK1 gene itself were primarily responsible for acquired resistance to BI2536 in a cultured human colon cancer cell line." (PMID 25198282, 2014). "In case of the APC colorectal tumors, Strebhardt and colleagues showed similar data also using the TCGA database, identifying one hundred colon cancer patient samples that harbor the APC non-sense mutations for which PLK1 expression and clinical data is also available." (PMID 30862113, 2019). "Recently, Plk1 has been implicated in the regulation of stem cell maintenance and proliferation, as inhibiting Plk1 activity impaired growth and induced apoptosis of neurospheres and of colon cancer initiating cells." (PMID 25537513, 2015). "It has been reported that pharmacological inhibition of PLK1 in colon carcinoma cells (HTC-116) induces p21 upregulation, leading to cell cycle arrest and, in turn, apoptosis or senescence depending on cellular context." (PMID 41300524, 2025). "More importantly, high PLK1 expression significantly improved the survival of patients with colon cancer expressing a truncated APC." (PMID 33996604, 2021). "It has been reported that PLK2 can phosphorylate Ser-137 of PLK1 to promote human colon cancer cell survival in cells with mitochondrial dysfunction." (PMID 35156101, 2021). "High PLK1 expression increases the survival of colon cancer patients expressing a truncated APC significantly." (PMID 29549256, 2018). "The efficacy of this clinically most advanced PLK1 inhibitor has been demonstrated in different colon cancer models, and various phase I trials in solid tumors including colon cancer have shown favorable pharmacokinetics and manageable toxicity." (PMID 29549256, 2018). "Here, we studied the role of PLK1 in colon cancer cells with CIN by using the PLK1 inhibitor BI6727 (volasertib) or RNAi." (PMID 29549256, 2018). "In colon cancer patients harboring a nonsense mutation within the APC gene which leads to the expression of a truncated APC protein, high PLK1 expression increased patients’s survival significantly." (PMID 29549256, 2018). "Here we study the role of PLK1 in colon cancer cells with chromosomal instability promoted by APC truncation (APC-ΔC)." (PMID 29549256, 2018). "To explore the role of PLK1 in colon cancer, we hampered its function in a well-established, APC-related colon cancer model by using pharmacological means or RNAi." (PMID 29549256, 2018). "We show here that both BI compounds induce senescence in visceral ASCs, in line with our previous observation that colon carcinoma HCT116 cells were senescent after a prolonged treatment with Plk1 inhibitors." (PMID 27713178, 2016). "An earlier study in 2013 found that PLK1 inhibitors could help treat colon cancer or early-stage lesions with high levels of inflammatory cell infiltration." (PMID 40612941, 2025). "They meditate polo-like kinase 1 (PLK1) to control necroptotic activity in colon cancer." (PMID 35884370, 2022). "Interestingly, PLK1 inhibitors demonstrated maximal efficiency over other targeted compounds and chemotherapeutic agents in inducing the death of colon cancer-initiating cells in vitro." (PMID 34065438, 2021). "To determine whether PLK1 overexpression is associated with chemoresistance in CRC, we examined the correlation between the PLK1 expression level and the cytotoxic effect of oxaliplatin in a panel of colon cancer cell lines." (PMID 34881526, 2021).
colon carcinoma (continued). "We believe that this work improves our understanding of how PLK1 inhibition can influence the fate of genetically instable colon cancer cells and might provide a rational to strengthen the SAC in aneuploid tumors for cancer treatment." (PMID 29549256, 2018). "Remarkably, the analysis of PLK1-depletion in colon cancer cells in culture and in an inducible RNAi model in transgenic mice demonstrated that cancer cells and primary cells differ clearly in their dependency to PLK1 supporting a key role for PLK1 in colorectal carcinogenesis." (PMID 29549256, 2018). "Based on our results in animal models, we hypothesized that PLK1 activity may impinge on the clinical outcome of colon cancer patients." (PMID 29549256, 2018). "To address if the p21 status is a direct factor for the efficacy of Plk1 inhibitors, we have chosen the isogenic colon cancer cell lines HCT116 p21+/+ and HCT116 p21−/−, as they contain comparable cellular context except the p21 status and are very well characterized." (PMID 25483104, 2015). "Hence, it would be extremely interesting to analyze whether Plk1 can also control APC localization in human cells, particularly considering that most sporadic colon cancers are attributable to APC mutations." (PMID 33135999, 2020). "However, it has been documented that adenomatous polyposis coli (APC) germline mutations cause aneuploidy and are responsible for familial adenomatous polyposis (FAP), while higher polo-like kinase 1 (PLK1) gene expression can increase the survival for colon cancer patient with a truncated APC." (PMID 31263147, 2019). "Thus confirming the fact that Plk1 can also play as a tumor suppressor in APC related colon tumors." (PMID 30862113, 2019). "For PLK isoenzymes other than PLK1 only sparse information on expression in various tumour entities is available, with only one study in mice reporting a relative loss of expression for PLK3 mRNA in colon carcinomas in comparison to adjacent normal colon mucosa." (PMID 14970859, 2004). "PLK1 inhibitors also synergistically with mTOR inhibitors to compensatively induce MYC expression, overcome the oxaliplatin resistance of colon cancer, and enhance the radiosensitivity of medulloblastoma." (PMID 40612941, 2025). "This study revealed that remimazolam promoted the cell-cycle progression and proliferation of HCT8 colon cancer cells by upregulating CDK1, PTTG1, CDC25C, CDK4, PLK1, PCNA, Ki67, RNASEH2B, FEN1, Cyclin D1,CD44 CDK2, CDKN3, CDC45, IQGAP3, and CDK6." (PMID 38725628, 2024). "In vivo, PLK1 inhibitors killed CD133(+) colon cancer cells, leading to complete growth arrest of colon cancer stem cell-derived xenografts, whereas chemotherapeutic agents only slowed tumor progression." (PMID 34065438, 2021). "Currently, PLK1 inhibitors mainly target mitosis and are predominantly used for breast and colon cancers, with no clinical benefits reported yet." (PMID 37744268, 2023). "In colon cancer cells with partial APC gene knockout, PLK1 inhibits tumor growth." (PMID 36267311, 2022). "Silencing of Plk1 did not significantly reduce active form of Aurora A/B in human colon cancer cells, suggesting Aurora A/B and Plk1 work in parallel during bufalin-induced mitotic arrest." (PMID 29568394, 2018). "Onvansertib is a novel oral, highly selective adenosine triphosphate (ATP) competitive Plk1 inhibitor that has demonstrated anti-tumorigenic activity in multiple types of solid tumors and hematologic malignancies, including AML, medulloblastoma, ovarian cancer, breast cancer, and colon cancer." (PMID 40166466, 2025).
lung adenocarcinoma (41 papers, 2014 to 2026). A carcinoma that arises from the lung and is characterized by the presence of malignant glandular epithelial cells. "PLK1 is associated with various malignant tumors, but its correlation with lung adenocarcinoma (LUAD) remains unclear." (PMID 41556056, 2026). "Down-regulation of KPNB1 induced by PLK1 inhibition caused apoptosis in lung adenocarcinoma." (PMID 36551208, 2022). "Higher methylation level of PLK1/3 promoter was associated with poor survival probability of patients with lung adenocarcinoma, while higher methylation level of PLK2/4 was significantly related to favourable survival probability of patients with lung adenocarcinoma." (PMID 34080290, 2021). "Further analysis sought to determine the prognostic value of PLK1 expression in 25 different cancer types, revealing a negative association between PLK1 expression and overall survival in 10 cancer types, including breast invasive carcinoma, lung adenocarcinoma, and pancreatic ductal adenocarcinoma." (PMID 37174744, 2023). "Researchers have discovered that the lncRNA SNHG14/hsa-miR-101-3p/KL/PLK1 regulatory axis plays a modulatory role in the immune microenvironment of lung adenocarcinoma." (PMID 41244907, 2025). "PLK1 inhibition suppresses the migration of A549 lung adenocarcinoma cells by decreasing MMP2 and VEGFA expression." (PMID 38355643, 2024). "The analysis demonstrated that PLK1 mRNA expression was significantly higher in SCLC cells compared to lung adenocarcinoma (LUAD) cells (p < 0.01)." (PMID 39085197, 2024). "PLK1 has emerged as a promising therapeutic target for lung adenocarcinoma due to its role in tumor growth, progression, and treatment resistance." (PMID 37744268, 2023). "Targeting PLK1 holds promise for overcoming treatment resistance and improving outcomes for patients with lung adenocarcinoma." (PMID 37744268, 2023). "Preclinical studies using PLK1 inhibitors have demonstrated their efficacy in inhibiting tumor growth, inducing apoptosis, and sensitizing lung adenocarcinoma cells to conventional treatments." (PMID 37744268, 2023). "We observed that PLK1/2/3/4 methylation in lung adenocarcinoma was inferior to that in normal sample." (PMID 34080290, 2021). "In summary, we herein identified the transcriptional and protein expression of PLK1/2/3/4 in lung adenocarcinoma and lung squamous cell carcinoma." (PMID 34080290, 2021). "Based on the methylation analysis, we further analysed the prognostic values of global methylation of PLK1/2/3/4 in lung adenocarcinoma and lung squamous cell carcinoma." (PMID 34080290, 2021). "In Hou lung Statistics, the most samples among six data sets, PLK1 expression was increased in lung adenocarcinoma with a fold change of 2.115 and in lung squamous cell carcinoma with a fold change of 2.741." (PMID 34080290, 2021). "The phosphorylation of vimentin was accompanied by the activation of PLK1 during TGF-β-induced EMT in lung adenocarcinoma." (PMID 33963314, 2021). "microRNA‐100 also increases sensitivity to docetaxel chemotherapy in lung adenocarcinoma cells through PLK1 protein." (PMID 33660436, 2021). "Using immunohistochemistry, the expression levels of PSMB6, HSPA9, DUT, CDK7, and PLK1 were found to be higher in lung adenocarcinoma tissues of patients, while the expression of FOLR2 was low, which was consistent with survival prediction." (PMID 34721732, 2021). "Disruption of PLK1 mitotic pathway in lung adenocarcinoma cells dramatically inhibited cell proliferation." (PMID 34080290, 2021). "Methylation analysis displayed that methylation of PLK1/2/3 genes remained a higher level in normal lung sample than that in lung adenocarcinoma." (PMID 34080290, 2021).